LYPD6 (LY6/PLAUR domain containing 6)
Description:
Acts as a modulator of nicotinic acetylcholine receptors (nAChRs) function in the brain. Inhibits nicotine-induced Ca(2+) influx through nAChRs. In vitro, specifically inhibits alpha-3:beta-4 and alpha-7 nAChR currents in an allosteric manner. Acts as a positive regulator of Wnt/beta-catenin signaling (By similarity).
Synonyms: MGC52057
Tractability: Antibody: UniProt places it where antibodies can reach, with high confidence; UniProt predicts a signal peptide or a membrane-spanning region; its Gene Ontology location is reachable by antibodies, with medium confidence.
Gene: Protein-coding gene on chromosome 2 (149,329,985 to 149,474,139, forward strand). Ensembl gene ENSG00000187123.
Subcellular location: Secreted; Cytoplasm; Cell membrane; Synapse, synaptosome; Membrane raft; Cell projection, dendrite; Perikaryon
Subcellular location (Human Protein Atlas): Cytosol; Predicted to be secreted
Gene Ontology:
Molecular function: acetylcholine receptor inhibitor activity; protein binding; acetylcholine receptor regulator activity
Biological process: positive regulation of canonical Wnt signaling pathway
Cellular component: cytoplasm; plasma membrane; membrane raft; perikaryon; dendrite; extracellular region; membrane; neuron projection; synapse
Genetic constraint (gnomAD): Loss-of-function variants: 13 observed, 19.18 expected, observed/expected ratio (o/e) 0.68, 90% interval 0.44 to 1.08. The upper end of that interval is the gene's LOEUF score, 1.08, which puts it in group 4 of 6, group 1 being the genes least tolerant of losing a copy. Missense variants: 180 observed, 207.82 expected, observed/expected ratio (o/e) 0.87, 90% interval 0.77 to 0.98. Synonymous variants: 69 observed, 78.49 expected, observed/expected ratio (o/e) 0.88, 90% interval 0.72 to 1.07.
Homologues: Orthologues: macaque LYPD6 (99% identical), dog LYPD6 (96% identical), pig LYPD6 (96% identical), guinea pig LYPD6 (96% identical), mouse Lypd6 (95% identical), rat Lypd6 (94% identical), chimpanzee LYPD6 (92% identical), rabbit LYPD6 (79% identical), tropical clawed frog lypd6 (67% identical), zebrafish lypd6 (67% identical). Paralogues in human: LYPD6B (36% identical).
Diseases named in the same sentence as LYPD6 in open-access papers:
LYPD6 is named in the same sentence as 17 diseases in open-access papers, as found by Europe PMC text mining. Sharing a sentence is not in itself a finding about the gene and the disease. The quoted sentences say what the papers report.
Anxiety (2 papers, 2019 to 2024). Intense feelings of nervousness, tension, or panic often arise in response to interpersonal stresses. "Mice receiving ws-Lypd6 exhibited impaired exploratory behavior, while both modulators caused acute context-dependent anxiety and impaired working and olfactory memory." (PMID 39433742, 2024). "We showed that increased abundance of Lypd6 and Lypd6b in the brain was associated with memory decline, anxiety, atrophy of hippocampal and amygdala dendritic spines, and downregulation of the cholinergic system." (PMID 39433742, 2024). "Thus, increased Lypd6 and Lypd6b level in the brain are linked to cholinergic system depression, neuronal atrophy, memory decline, and anxiety." (PMID 39433742, 2024). "The other membrane protein, LYPD6, is enriched in synaptic loci, and Lypd6 KO mice show reduced anxiety-like behavior and enhanced response to nicotine." (PMID 31455729, 2019). "In line with our data, LYPD6 knockout in the brain resulted in a reduction of anxiety in mice." (PMID 39433742, 2024). "Lypd6 regulates juvenile visual plasticity, anxiety, and nociception." (PMID 39433742, 2024). "Thus, we can assume that impaired memory and anxiety of mice observed here may be driven at least partially by dendritic spine downregulation after ws-Lypd6 and ws-Lypd6b administration." (PMID 39433742, 2024).
schizophrenia (2 papers, 2019 to 2024). A major psychotic disorder characterized by abnormalities in the perception or expression of reality. "LYPD6 was downregulated in schizophrenia and during normal aging." (PMID 39433742, 2024).
autism (1 paper, 2024). Persistent deficits in social interaction and communication and interaction as well as a markedly restricted repertoire of activity and interest as well as repetitive patterns of behavior. "Enhanced mRNA Lypd6 and Lypd6b expression in the brain was found in patients with autism and some other pathologies." (PMID 39433742, 2024). "Bioinformatic analysis revealed increased expression of LYPD6 and LYPD6B mRNA expression in the brains of patients with different neurological and psychiatric disorders: autism, Huntington’s and Parkinson’s diseases, and in epilepsy." (PMID 39433742, 2024). "Bioinformatic analysis revealed increased or decreased LYPD6 and LYPD6B expression in different neuropsychiatric disorders: autism, Parkinson’s and Huntington’s diseases, epilepsy, and others." (PMID 39433742, 2024). "Increased LYPD6 and LYPD6B expression was revealed in autism and other disorders." (PMID 39433742, 2024).
cognitive deficits (1 paper, 2014). "This could also help to explain the impact of Lypd6 over-expression on cognitive processes as well as the cognitive deficits in patients with CNVs in the Lypd6 locus." (PMID 25359633, 2014).
developmental delay (1 paper, 2012). "Interestingly, LYPD6 is also located within a microduplication region linked to developmental delay." (PMID 23145134, 2012).
memory impairment (1 paper, 2024). "Thus, an increase of Lypd6 and Lypd6b levels in the brain leads to stress induction and memory impairment." (PMID 39433742, 2024).
tumor (2 papers, 2022 to 2024). "Regardless of luminal subtype (A/B), LM cells had increased expression of ELOVL5, EFHD1, NEK10, LYPD6 and NOVA1, among others, relative to the tumor cells." (PMID 39478117, 2024).
neurological disorders (1 paper, 2024). "The correlation between manifestations of neurological disorders and LYPD6 and LYPD6B expression deserves further attention." (PMID 39433742, 2024). "Here, to establish possible relationships between Lypd6 or Lypd6b overexpression in the brain and neurological disorders, we performed bioinformatic analysis of tissues of patients with different neuropsychiatric diseases from the Gene Expression Omnibus." (PMID 39433742, 2024). "To model the upregulation of Lypd6 and Lypd6b in the brain during neurological diseases, we used a mouse model with intracerebroventricular delivery of recombinant water-soluble domains of Lypd6 and Lypd6b (ws-Lypd6 and ws-Lypd6b) into the brain." (PMID 39433742, 2024). "Thus, our data indicate that Lypd6 and Lypd6b may mediate at least some behavioral aspects of certain neurological disorders." (PMID 39433742, 2024).
LYPD6 also shares sentences with these, for which no sentence is quoted: cancer (1 paper); cognitive decline (1); epilepsy (1); Huntington disease (1); infection (1); melanoma (1); Parkinson disease (1); Parkinson’s (1); psychiatric disorder (1).